DDR2 (discoidin domain receptor tyrosine kinase 2)
Diseases named in the same sentence as DDR2 in open-access papers (continued):
Sharing a sentence is not in itself a finding about the gene and the disease.
cancer (continued). "However, the exact function of DDR2 in driving cancer metastatic progression remains unclear." (PMID 36713812, 2022). "Many of the top overexpressed (e.g., FSTL1, TNS1, DDR2, or VWF) or underexpressed genes were suggested to promote invasion and/or metastasis in different cancer types." (PMID 36359790, 2022). "Further in vivo analysis of cancer development during treatment using specific DDR1 or DDR2 inhibitors, such as 7rh, 2.45, or WRG-28, in different cancers are needed." (PMID 33917302, 2021). "It should be noted that most of COL11A1 signaling molecules are also critical regulators of cancer stemness phenotype (e.g., TGFβ, TWIST, c/EBPb, DDR2, Akt, Scr)." (PMID 33668097, 2021). "In fact, studies from Longmore group has shown that DDR2 activation through COL1 interaction was able to stabilize SNAIL1, a transcription factor involved in the induction of EMT, thus leading to cancer cell migration and invasion." (PMID 35004699, 2021). "In neuronal cells, the cancer-related gene SLIT2 was found to be upregulated, as were six other cancer-related genes (PDGFRA, DDR2, RSPO3, IL6ST, NTRK2, and HEY1) in cardiomyocytes and one cancer-related gene (HSD3B1) in hepatocyte-like cells." (PMID 32127560, 2020). "Here, we review recent findings on the metastatic role of the collagen receptors Discoidin Domain Receptors 1 and 2 (DDR1 and DDR2) in CRC and discuss the therapeutic value of targeting these receptor tyrosine kinases in this cancer." (PMID 32117772, 2020). "both DDR1b and DDR2 increased the levels of CTGF, a key matricellular protein in cancer progression and fibrosis." (PMID 32047176, 2020). "Despite these, whether collagen‐activated DDR2 signaling and ECM stiffness‐induced mechanosensing exert similar effects on cancer cell behavior and whether they operate through analogous mechanisms remain elusive." (PMID 38538106, 2024). "By comparing focal SCNAs in matched NSCLC-BM pairs, we identified putative BM-driving alterations affecting multiple cancer genes, including several potentially targetable alterations in genes such as CDK12, DDR2, ERBB2, and NTRK1, which we validated in an independent cohort of 84 BM samples." (PMID 36561283, 2022). "DDR1 activation induces Src, Notch and IKK signaling pathway, DDR2 promotes oncogenic signaling via mTORC2 and AKT pathway, and recent findings have demonstrated that DDR-collagen signaling plays an important role in cancer progression and metastasis." (PMID 35008401, 2022). "DDR2 in PCa may stimulate bone resorption by up-regulating RANKL, and promote the adhesion between cancer cells and type I collagen, which could induce bone metastasis." (PMID 34860853, 2021). "DDR2 is required to elaborate linear invadosomes in endothelial cells and to facilitate matrix degradation in association with VEGF (Vascular Endothelial Growth Factor), but it is not known if DDR2 plays the same role in cancer cells." (PMID 33917302, 2021). "The 7rh benzamide was synthesized using a palladium-catalyzed Sonogahira coupling, and showed a significant suppressive effect on the proliferation of DDR1-expressing cancer cells, but not DDR2-, Bcr-Abl-, or c-Kit-expressing cells." (PMID 28143619, 2017). "Thus, our results on mechanotranscriptional regulation of DDR2 expression by matrix stiffness seem to point to a new concept regarding how a mechanically permissive environment affects EMT and cancer progression." (PMID 28754957, 2017). "Additionally, IL-22 upregulates expression of Erk1/2-independent genes such as Discoidin domain receptor tyrosine kinase 2 (DDR2), Lipocalin 2 (LCN2), and Leucine-rich alpha-2-glycoprotein 1 (LRG1), known for their involvement in the modulation of specific cancer hallmarks." (PMID 40806452, 2025). "However, whether DDR2 and ECM biomechanics could interact to regulate cancer cell behavior is yet to be determined." (PMID 38538106, 2024).
cancer (continued). "Interestingly, the role of DDR2 in MT1-MMP activation is rather limited to non-transformed fibroblasts as DDR inhibition does not affect MT1-MMP activation in cancer cells." (PMID 28270508, 2017). "Circ-LAMP1 activated domain receptor tyrosine kinase 2 (DDR2) by sponging miR-615-5p, which directly targeted DDR2, a member of the receptor tyrosine kinase (RTK) family, therefore, circ-LAMP1 might be an oncogene in T-LBL, as RTK initiated a signaling cascade closely related to cancer progression." (PMID 32518520, 2020). "Finally, although the findings reported here need to be tested in additional models of cancer, the pro-growth effect of the DDR/COL1 axis has been recently validated in our laboratory with human pancreatic MiaPaCa-2 cells engineered to express DDR1b or DDR2 (manuscript in preparation)." (PMID 32047176, 2020). "Because the glycolytic pathway is critical for cancer cell proliferation and maintenance, BT549 cells may have acquired redundant regulatory mechanisms to maintain glycolytic flux without DDR2." (PMID 36713812, 2022).
adenocarcinoma (5 papers, 2014 to 2025). A common cancer characterized by the presence of malignant glandular cells. "DDR2 (Discoidin Domain Receptor tyrosine kinase 2) is a collagen-activated RTK whose dysregulation promotes EMT and engages PI3K/AKT and RAS/MEK/ERK signaling; evidence is strongest in lung squamous carcinoma and occasionally in adenocarcinoma." (PMID 41154602, 2025).
breast (3 papers, 2016 to 2022). "In the literature, DDR2 mutations are found in 4% of lung SCC and in 1% of lung ADC, without hotspot mutations." (PMID 28619094, 2017).
Renal disease (3 papers, 2022). "In the 9% of the patients that had renal disease, DDR2 expression was already decreased in the thickened aortic valve tissue to similar levels observed in the calcified tissue of patients with normal renal function." (PMID 35751904, 2022). "Interestingly, angiotensin II—which is upregulated in many mouse models of kidney disease—can induce expression of DDR2 and can promote secretion of IL-15 in primary renal parenchymal cells." (PMID 36249782, 2022). "Although not directly investigated in kidney disease, increasing evidence implicates DDR2 in lipid physiology." (PMID 36249782, 2022). "In contrast to DDR1, whether and where DDR2 expression is upregulated in subjects with kidney disease has not been investigated." (PMID 36249782, 2022).
cardiovascular disease (1 paper, 2021). "Considering that DDR2 is present in the atherosclerotic plaques of humans and is associated with collagen Ι-induced secretion of MMP-2, the clinical role of DDR2 in cardiovascular disease should be elucidated in further experiments." (PMID 34956435, 2021). "In conclusion, we found high expression of DDR2 in atherosclerotic plaques of human and various animal models, and DDR2 in VSMCs was involved with collagen I-induced secretion of MMP-2, suggesting that the clinical role of DDR2 in cardiovascular disease should be elucidated in further experiments." (PMID 34956435, 2021).
gastrointestinal tumours (1 paper, 2018).
neurodegenerative disease (1 paper, 2023). A disorder of the central nervous system characterized by gradual and progressive loss of neural tissue and neurologic function. "Intriguingly, DDR2 shares signalling partners with the neurodegenerative disease risk gene, TREM234, and both genes have functions in bone metabolism and neurodegeneration." (PMID 37919278, 2023). "Our findings add DDR2 to the growing list of neurodegenerative disease genes also involved in bone modelling." (PMID 37919278, 2023).
neurological disease (1 paper, 2023). "There are still limitations of understanding the relationship of DDR2 and COL1 and its association with a neurological disease by meningeal fibroblast‐mediated matrix remodeling via glycation." (PMID 36852525, 2023).
DDR2 also shares sentences with these, for which no sentence is quoted: nasopharyngeal carcinoma (3 papers); acute myeloid leukemia (2); endometrial cancer (2); leukaemia (2); metastatic tumor (2); small cell lung carcinoma (2); alcohol (1); anaplastic large cell lymphoma (1); angiosarcoma (1); atrial fibrillation (1); B-cell NHL (1); cardiac hypertrophy (1); chordoma (1); cutaneous squamous cell carcinoma (1); Epiphyseal dysplasia (1); Escobar syndrome (1); genetic disorder (1); heart disease (1); hepatoblastoma (1); Hodgkins lymphoma (1); hyperlipidemia (1); Hypertension (1); idiopathic pulmonary fibrosis (1); invasive carcinoma (1); large cell carcinoma (1); liver cirrhosis (1); lymphoma (1); neurodevelopmental disorder (1); oral cancer (1); pancreatic adenocarcinoma (1).
A further 11 diseases each share a sentence with DDR2 in 1 paper.